HLA-DPA1 (major histocompatibility complex, class II, DP alpha 1)
Diseases named in the same sentence as HLA-DPA1 in open-access papers (continued):
Sharing a sentence is not in itself a finding about the gene and the disease.
adrenocortical tumors (2 papers, 2020 to 2022). "Clinical study on adrenocortical tumors (ACT) indicated low expression of HLA-DPA1 was associated with poor prognosis." (PMID 32972413, 2020). "Low expression of HLA-DPA1 is associated with pediatric adrenocortical tumors." (PMID 35486660, 2022).
ankylosing spondylitis (2 papers, 2019 to 2024). An autoimmune chronic inflammatory disorder characterized by inflammation in the vertebral joints of the spine and sacroiliac joints. "The HLA-DPA1 locus has been particularly linked to ankylosing spondylitis, a type of chronic inflammatory rheumatic disease." (PMID 30972099, 2019).
bipolar disorder (2 papers, 2012 to 2016). A disorder of the brain that causes unusual shifts in mood, energy, activity levels and the ability to carry out day-to-day tasks. "This supports some shared immune alterations in brain for bipolar disorder and schizophrenia, and the observed strong genetic association of SZ to the MHC region supports a role of HLA-DPA1 as a potential susceptibility gene." (PMID 26998349, 2016). "Within this interval we examined the expression of two MHC II genes (HLA-DPA1 and HLA-DRB1) in brain from individual subjects with schizophrenia (SZ), bipolar disorder (BD), major depressive disorder (MDD), and controls by differential gene expression methods." (PMID 26998349, 2016).
diabetic kidney disease (2 papers, 2023 to 2025). Progressive kidney disorder caused by vascular damage to the glomerular capillaries, in patients with diabetes mellitus. "Prior research has indicated that HLA-DPA1 is associated with RA and SLE, and it may also contribute to the pathogenesis of diabetic kidney disease." (PMID 40149558, 2025).
graft versus host disease (2 papers, 2016 to 2026). An immune system disorder that occurs after allogeneic hematopoietic stem cell transplant and is a reaction of donor immune cells against host tissues. "In contrast, HLA-DPA1 exhibited positive enrichment in immune and metabolic pathways, including lysosome, oxidative phosphorylation, Leishmania infection, and graft-versus-host disease." (PMID 41601671, 2026). "The pathway enrichment for trans-eQTL egenes was largely driven by HLA genes (e.g. HLA-DRB4, HLA-C, HLA-B, HLA-DPA1, and HLA-DQA1 appear in the gene sets for graft-versus-host disease, allograft rejection, and cell adhesion molecules)." (PMID 27140173, 2016).
lung carcinoma (2 papers, 2023 to 2024). "Additionally, a meta-analysis of data within the Lung Cancer Explorer (LCE) database also demonstrated that decreased expression of HLA-DPA1 was related to poor OS for patients with LUAD." (PMID 37899135, 2023).
Obesity (2 papers, 2022). Accumulation of substantial excess body fat. "Adipocytes from humans with obesity had increased expression of multiple MHCII-related genes (CIITA, HLA-DPA1, CD74, CD80) in both VAT and SAT." (PMID 36153324, 2022).
osteosarcoma (2 papers, 2018 to 2023). A usually aggressive malignant bone-forming mesenchymal neoplasm, predominantly affecting adolescents and young adults. "HLA-DPA1 and TYROBP, the hub genes in PPI network were regulated by MiR-96, but their function were not researched in osteosarcoma too." (PMID 29760609, 2018).
periodontitis (2 papers, 2022). An acute or chronic inflammatory process that affects the tissues that surround and support the teeth. "The 115 DEPs revealed 4 significantly enriched pathways (p value<0.05) in which Staphylococcus aureus infection signalling pathway, including FCGR3B and HLA-DPA1, exhibited a significant difference in gingival tissues from healthy and periodontitis groups." (PMID 36016933, 2022).
schizophrenia (2 papers, 2012 to 2016). A major psychotic disorder characterized by abnormalities in the perception or expression of reality. "The HLA-DPA1 eQTL is located within a large linkage disequilibrium block that has an irrefutable association with schizophrenia." (PMID 26998349, 2016). "A highly significant SNP associated with schizophrenia is 15 kB downstream of the eQTL for HLA-DPA1 and D’ is 0.82 between rs112790520, a proxy for rs155327711, and rs9277341." (PMID 26998349, 2016).
tuberculosis (2 papers, 2019 to 2023). A chronic, recurrent infection caused by the bacterium Mycobacterium tuberculosis.
adrenocortical adenomas (1 paper, 2019). "Interestingly, HLA-DPA1 is predominantly expressed in hematopoietic infiltrating cells in adrenocortical adenomas." (PMID 31694270, 2019).
alcohol addicts (1 paper, 2024). "Of these, HLA-DPA1 and HLA-DPB1 showed stable expression patterns in alcohol addicts." (PMID 38448893, 2024).
allergic disease (1 paper, 2019). An immune response that occurs following re-exposure to an innocuous antigen, and that requires the presence of existing antibodies against that antigen. "Genetic variants at HLA-DPA1 have been associated with a number of traits, including allergic disease and systemic sclerosis, and upregulated protein expression of HLA-DP molecules has been reported by a small study in pSS salivary gland tissue." (PMID 31428085, 2019).
brucellosis (1 paper, 2024). Brucellosis is a bacterial infection that spreads from animals to people via unpasteurized dairy products or by exposure to contaminated animal products or infected animals. "In agreement with this, the expression levels of phagocytosis‐ and antigen‐presentation‐associated genes (e.g., CIITA, RFX5, HLA‐DPA1, WASF2) were reduced in brucellosis patients." (PMID 39135683, 2024).
colon adenoma (1 paper, 2022). An adenoma that arises from the colon. "Our results point out that both HLA-DPA1 and HL-DQB1 declined in colon adenomas." (PMID 35486660, 2022).
endometriosis (1 paper, 2025). The growth of functional endometrial tissue in anatomic sites outside the uterine body. "Infertile patients with or without endometriosis demonstrated reduced HLA-DPA1 and HLA-DPB1 expression in their endometriums." (PMID 40165344, 2025).
hepatitis C infection (1 paper, 2011). "The progression-related sub-network deregulated in hepatitis C infection stage was constructed with four nodes (HLA-DQA1, HLA-DQB1, HLA-DPA1 and CD74) and interactions among them." (PMID 21526182, 2011).
hypothyroidism (1 paper, 2020). Abnormally low levels of thyroid hormone. "Hypothyroidism has 4 genes (HLA-DPA1, HLA-DQB1, HLA-DQA1, and HLA-DPB1, where two have 5% of predictor variance each and two have 1% each) out of its top 17 genes included among the 641 potentially problematic genes, while 8% is the highest value of predictor variance accounted for by a single gene." (PMID 32694572, 2020).
influenza (1 paper, 2024). An acute viral infection of the respiratory tract, occurring in isolated cases, in epidemics, or in pandemics; it is caused by serologically different strains of viruses (influenzaviruses) designated A, B, and C, has a 3-day incubation period, and usually lasts for 3 to 10 days. "Functional studies showed that, unlike HLA DPA1, PCOLCE2 levels were significantly higher in the severe influenza group compared to the non-severe influenza group." (PMID 39374805, 2024).
Kawasaki disease (1 paper, 2024). A rare inflammatory disease characterized by an acute febrile, systemic, self-limiting, medium-vessel vasculitis primarily affecting children. "Consistent with our findings, a study reveals that CM highly express S100A8, S100A9, and S100A12, IM express HLA-DQA1 and HLA-DPA1 and NCM mainly express CD16, demonstrating a distinct transcriptome across monocyte subsets in Kawasaki disease." (PMID 39318997, 2024).
liver fibrosis (1 paper, 2022). "In our study, we found that HLA-DPA1 and HLA-DPB1 differed significantly in groups with different degrees of liver fibrosis." (PMID 36406135, 2022).
lupus nephritis (1 paper, 2021). Glomerulonephritis in the context of systemic lupus erythematosus. "Further analysis revealed that HLA-DPA1, IL10RA, and IRF8 were differentially expressed in different pathological staging samples of lupus nephritis." (PMID 34692653, 2021).
lymph node metastasis (1 paper, 2023). "We also observed correlations between low HLA-DPA1 expression and the clinical stages, histological subtype, and lymph node metastasis categories in patients with LUAD (P < 0.05)." (PMID 37899135, 2023). "Our analysis revealed decreased HLA-DPA1 expression in LUAD tissues, associated with gender, race, age, smoking history, clinical stage, histological type, and lymph node metastasis of patients with LUAD." (PMID 37899135, 2023).
male infertility (1 paper, 2017). The inability of the male to effect fertilization of an ovum after a specified period of unprotected intercourse. "Conversely, some hypermethylated genes (such as, DENND2D and LOC401127) and hypomethylated genes (such as, HLA-DPA1 and COL18A1) have not previously been associated with male infertility, which may provide novel insight into the etiology of idiopathic SO." (PMID 28553232, 2017).
multiple sclerosis (1 paper, 2023). A progressive autoimmune disorder affecting the central nervous system resulting in demyelination. "HLA-DPA1 was identified as a common drug target for both Sjogren's syndrome and multiple sclerosis in a previous study, while another study more directly by weighted gene co-expression network (WGCNA) and linkage map (CMap) of illustrating HLA-DPA1 as a drug target for RA." (PMID 37697373, 2023).
nodular sclerosis (1 paper, 2022). "In our study, genes related to major histocompatibility complex (MHC) class I and II machinery/biosynthesis such as HLA-DRA, CTSS, HLA-DPA1, HLA-DPB1, CTSC, B2M genes were expressed at higher levels in the mixed-cellularity subtype than in nodular sclerosis subtype at diagnosis." (PMID 36230815, 2022).
prostate carcinoma (1 paper, 2021). A carcinoma that arises from epithelial cells of the prostate gland. "Thus, the present study aimed to determine the significance of HLA-DPA1 rs3077 (A/G) SNP with the risk and/or severity of prostatic cancer." (PMID 33976942, 2021).
pulmonary arterial hypertension (1 paper, 2019). Pulmonary arterial hypertension (PAH) is a group of diseases characterized by mean pulmonary artery pressure >20 mmHg and elevated pulmonary arterial resistance leading to right heart failure. "This is the first study to report that common genetic variation at loci in an enhancer near SOX17 and in HLA-DPA1/DPB1 is associated with pulmonary arterial hypertension." (PMID 30527956, 2019). "Through a meta-analysis of 11 744 individuals, we have established loci at an enhancer upstream of SOX17 and at HLA-DPA1/DPB1 associated with pulmonary arterial hypertension disease risk." (PMID 30527956, 2019). "Polymorphic variation at the HLA-DPA1/DPB1 locus is strongly associated with both the age at diagnosis and prognosis in pulmonary arterial hypertension." (PMID 30527956, 2019). "We investigated whether the HLA-DPA1/DPB1 and SOX17 variants affect clinical outcomes in pulmonary arterial hypertension, specifically all-cause mortality." (PMID 30527956, 2019). "Both the SOX17 and HLA-DPA1/DPB1 loci reached genome-wide significance in the discovery analyses; our cross-validation strategy confirmed that the same alleles were more frequent in pulmonary arterial hypertension than in other disease or population controls in both analyses." (PMID 30527956, 2019).
thrombosis (1 paper, 2023). "A previous report showed potential correlations between HLA-DPB1 and HLA-DPA1 and thrombosis and ANCA-associated vasculitide (AAV)-associated thrombus formation." (PMID 37539039, 2023).
vitiligo (1 paper, 2021). Generalized well circumscribed patches of leukoderma that are generally distributed over symmetric body locations and is due to autoimmune destruction of melanocytes. "Using Beagle 4.1, we successfully imputed the SNV, CNV, two–digit and four–digit alleles of HLA genes (HLA-A, HLA-B, HLA-C, HLA-DQA1, HLA-DQB1, HLA-DPA1, HLA-DPB1, HLA-DRB1) and amino acids of 2810 vitiligo subjects (1117 cases, 1693 controls) and 2739 SLE subjects (1,693 controls and 1,046 cases)." (PMID 35082778, 2021).
tumor (58 papers, 2009 to 2025). "The correlation between the HLA-DPA1 overexpression and immune cell markers in the context of tumor purity." (PMID 37899135, 2023). "The adjusted results based on tumor purity showed a significant correlation between HLA-DPA1, CD4, and all immune cell types (all P < 0.05)." (PMID 36627705, 2023). "We also observed that the 4 prognosis-associated genes RHOB, TALDO1, HLA-DPA1, and TKT were simultaneously elevated in the tumor and peripheral blood in patients with HCC." (PMID 35856557, 2022). "Validation analysis indicated that HLA-C, HLA-DPA1, HLA-E, HLA-F and HLA-G were associated with HCC prognosis of overall survival (all P ≤ 0.05, elevated 0.988 and 0.997 multiples compared to non-tumor tissues, respectively)." (PMID 31602270, 2019). "The positive correlation of the HLA-DPA1/CD4 expression with some immune cells with anti-tumor effects such as NK cells may explain this phenomenon." (PMID 36627705, 2023). "Additionally, a significant inverse correlation was observed between HLA-DPA1 expression and tumor purity (r = −0.366)." (PMID 37899135, 2023). "Furthermore, 4 common prognosis-associated genes (RHOB, TALDO1, HLA-DPA1, and TKT) were significantly overexpressed in the paired tumor tissue and blood." (PMID 35856557, 2022). "We obtained results on the correlation between TPPP3 expression and marker genes of tumor infiltration-associated immune cells, including CD8+T cells (CD8A and CD8B), B cell (CD19 and CD79a), and Myeloid dendritic cell (HLA-DPB1, HLA-DQB1, HLA-DRA, HLA-DPA1, CD1C, NRP1, and ITGAX)." (PMID 33083464, 2020). "Here, the tumor cells elevate expression of immune signaling MHC II molecules (CD74, HLA-DRB1, HLA-DPA1) and immune-regulating secretory proteins (REG4, AGR2, AGR3), with AGR2 and REG4 specifically upregulated in RCRC." (PMID 41450739, 2025). "The transcriptomic profile that we found in tumour-reactive CD137+ CD8+ T cells suggested an exhausted/activated-like phenotype with increased expression of TNFRSF9, LAG3, PDCD1, TIGIT and HLA-DPA1/HLA-DQA1." (PMID 38986249, 2024). "TIMELESS expression was significantly negatively correlated with neutrophil biomarkers (CEACAM8) and dendritic cell biomarkers (HLA-DPB1, HLA-DQB1, HLA-DRA, HLA-DPA1, CD1C) in TCGA LUAD tumor tissues." (PMID 38261568, 2024). "The top 100 genes found to be co-expressed with CD74 were examined using GEPIA2.0, finding that the top five genes (HLA-DMA, HLA-DPA1, HLA-DPB1, HLA-DRA, and HLA-DRB1) were highly correlated with CD74 in most tumor types." (PMID 38582956, 2024). "We found three Hla-genes (Hla-dra, Hla-dpa1 and Hla-dpb1) related with MHC which are involved in the immune suppression and play a crucial role in tumor immune escape." (PMID 37740230, 2023). "Cluster Fib_5 prominently expressed MHC-II genes (HLA-DQA1, HLA-DQA2, HLA-DQB1, HLA-DRB5, HLA-DRB1, HLA-DRA, HLA-DPA1, and HLA-DPB1), indicating their role as antigen-presenting cells with tumor-suppressing effects." (PMID 37533434, 2023). "Neutrophils in tumour‐invaded TDLN highly expressed AP (CD74 and HLA‐DPA1/DQA1), pro‐angiogenesis (VEGFA) and immunosuppressive (TGFBI)‐related genes." (PMID 37491740, 2023). "The six genes of the signature belonged to different functional immune-related groups: antigen presentation (HLA-DPA1 and CD1C), innate immune response (TLR7), type II interferon signaling (IFNB1), tumor marker (MMP2), and proliferation marker (MKI67)." (PMID 34209514, 2021). "The six genes belonged to different functional groups: antigen presentation (HLA-DPA1 and CD1C), innate immune response (TLR7), type II interferon signaling (IFNB1), tumor marker (MMP2), and proliferation marker (MKI67)." (PMID 34209514, 2021). "Meanwhile, HLA-DPA1, HLA-DQA1, HLA-DPB1 and HLA-DMB belong to MHC class II, one of the most important components in tumor-immune interactions." (PMID 33066530, 2020).
tumor (continued). "Additionally, ENHO was positively co-expressed with MHC class II presentation genes (including HLA-DMA, HLA-DOA, HLA-DPA1, HLA-DPB1, and HLA-DRB1), supporting its role in promoting anti-tumor immunity." (PMID 40647442, 2025). "Furthermore, IHC analysis revealed an up-regulation of immune-related factors HLA-DPA1 and CIITA in tumor tissues overexpressing AEG-1." (PMID 39483471, 2024). "TIMELESS expression in LUAD tumor tissues was significantly negatively correlated with neutrophil biomarkers, dendritic cell biomarkers (HLA-DPB1, HLA-DQB1, HLA-DRA, HLA-DPA1, CD1C) and an immunophenoscore that predicted outcomes associated with the use of immune checkpoint inhibitors." (PMID 38261568, 2024). "It is worth noting that the interaction between HLA‐II molecules (such as HLA‐DRA, HLA‐DRB1, HLA‐DRB5, HLA‐DQB1, HLA‐DPB1, HLA‐DPA1, HLA‐DMB and HLA‐DMA) and the receptor CD4 was exclusively detected in the cell communication between malignant cells from single‐primary tumours and Tregs." (PMID 39601163, 2024). "We also noticed that MHCII molecule including HLA-DPA1, HLA-DRB1, HLA-DQA1 and CD74 were significantly downregulated in this cluster of macrophages, which may contribute to sub-optimal tumor antigen presentation." (PMID 37957625, 2023). "In addition, we observed that several MHC family members, such as HLA-DRA, HLA-DRB1, HLA-DPA1 and HLA-DPB1, were highly expressed in response tumour samples." (PMID 36581917, 2022). "We adjusted these results based on tumor purity, revealing strong and significant correlations between CD96 and CD8+ T cell markers (CD8A), general T cell markers (CD3D, CD3E, CD2), DC markers (HLA-DPB1, HLA-DRA, HLA-DPA1) in LGG." (PMID 33680972, 2021). "When comparing our gene expression analyses and genetic analyses, the cancer genes HLA-DPA1, HLA-DMB, DNAJA4, LY86, HCLS1, GABBR1, NUDT16 showed upregulation in tumor tissue compared to cell subpopulations and are located in chromosomal regions that showed losses in GSC and CD133pos./CD15pos. cells." (PMID 32634135, 2020). "Overall, the functional enrichment analysis results suggested that the cluster of genes co-expressed with HLA-DPA1 and -DRA may promote anti-tumor immune response through antigen processing and presentation via MHC class II." (PMID 31212865, 2019). "Furthermore, an analysis utilizing the TSIDB database uncovered a significant correlation between AEG-1 and several key factors, including the tumor-promoting cell Th2, immune activator IL6, CXCR4, immunosuppressants CTLA4, IL1, IDO1, LAG3, PDCD1, TGFB1, and the DHC molecule HLA-DPA1." (PMID 39483471, 2024). "In addition, HLA-DQA1 and HLA-F showed prognostic values for overall survival, and HLA-A, HLA-C, HLA-DPA1 and HLA-DQA1 showed prognostic values for recurrence-free survival (all P ≤ 0.05, elevated 0.927, 0.992, 1.023, 0.918, 0.937 multiples compared to non-tumor tissues, respectively)." (PMID 31602270, 2019).